TXNDC11 (thioredoxin domain containing 11)
Description:
May act as a redox regulator involved in DUOX proteins folding. The interaction with DUOX1 and DUOX2 suggest that it belongs to a multiprotein complex constituting the thyroid H(2)O(2) generating system. It is however not sufficient to assist DUOX1 and DUOX2 in H(2)O(2) generation.
Synonyms: EFP1
Tractability: Antibody: UniProt predicts a signal peptide or a membrane-spanning region; the Human Protein Atlas places it where antibodies can reach. PROTAC: ubiquitination databases record sites on it; its protein half-life has been measured.
Gene: Protein-coding gene on chromosome 16 (11,679,079 to 11,742,907, reverse strand). Ensembl gene ENSG00000153066.
Subcellular location: Endoplasmic reticulum membrane
Subcellular location (Human Protein Atlas): Cytosol; Plasma membrane
Pathways (Reactome):
Metabolism: Thyroxine biosynthesis
Gene Ontology:
Molecular function: protein binding
Cellular component: cytosol; plasma membrane; endoplasmic reticulum membrane
Genetic constraint (gnomAD): Loss-of-function variants: 56 observed, 58.11 expected, observed/expected ratio (o/e) 0.96, 90% interval 0.78 to 1.2. The synonymous counts are far from expectation, so gnomAD's model fits this gene poorly and the ratio says little. Missense variants: 1,276 observed, 1,107.4 expected, observed/expected ratio (o/e) 1.15, 90% interval 1.1 to 1.21. Synonymous variants: 532 observed, 448.59 expected, observed/expected ratio (o/e) 1.19, 90% interval 1.1 to 1.27.
Homologues: Orthologues: chimpanzee TXNDC11 (99% identical), macaque TXNDC11 (97% identical), pig TXNDC11 (88% identical), rabbit TXNDC11 (85% identical), guinea pig TXNDC11 (84% identical), mouse Txndc11 (82% identical), dog TXNDC11 (82% identical), rat Txndc11 (81% identical), tropical clawed frog txndc11 (54% identical), zebrafish txndc11 (37% identical), Caenorhabditis elegans pdi-1 (8% identical), Caenorhabditis elegans M04D5.1 (6% identical), and 2 more. Paralogues in human: PDIA2 (10% identical), P4HB (9% identical), PDILT (9% identical), PDIA4 (9% identical), PDIA3 (8% identical), TMX4 (7% identical), PDIA5 (7% identical), PDIA6 (7% identical), TXNDC5 (7% identical), TMX1 (6% identical), ERP44 (6% identical), TMX3 (6% identical), and 1 more.
Diseases named in the same sentence as TXNDC11 in open-access papers:
TXNDC11 is named in the same sentence as 7 diseases in open-access papers, as found by Europe PMC text mining. Sharing a sentence is not in itself a finding about the gene and the disease. The quoted sentences say what the papers report.
asthma (1 paper, 2025). "ITM2C, TXNDC5, and TXNDC11, though less studied in asthma, are involved in the endoplasmic reticulum secretory machinery of plasma cells, coordinating protein folding, quality control, and trafficking to support high-rate antibody synthesis and secretion." (PMID 40950420, 2025).
glioma (1 paper, 2023). A benign or malignant brain and spinal cord tumor that arises from glial cells (astrocytes, oligodendrocytes, ependymal cells). "The current study evaluated glioma patients treated in our institution between 2010 and 2020 and found that high TXNDC11 expression was associated with advanced-grade glioma." (PMID 37686174, 2023). "In summary, high TXNDC11 expression is associated with high-grade glioma and poor prognosis." (PMID 37686174, 2023). "In light of exploring the diverse impacts of TXNDC11, it is important to note that our study aimed to comprehensively understand its role in glioma cell behaviours." (PMID 37686174, 2023). "Multivariate analysis revealed that in addition to the WHO grade, TXNDC11 protein expression was also an independent prognostic factor of glioma." (PMID 37686174, 2023). "Multivariate analysis revealed that TXNDC11 expression was an independent prognostic factor for gliomas." (PMID 37686174, 2023). "Further, TXNDC11 expression is an independent prognostic factor for gliomas." (PMID 37686174, 2023).
myeloma (1 paper, 2022). "In addition, per the Cancer Dependency Map28, myeloma plasma cells appear genetically dependent on TXNDC11 for proliferation." (PMID 35840578, 2022). "For example, TXNDC11 and CCR10 protein levels appear stable across drug treatments in comparison to canonical myeloma markers BCMA and CD138/SDC1." (PMID 35840578, 2022).
tumor (4 papers, 2021 to 2023). "High levels of TXNDC11 protein expression were significantly associated with World Health Organization (WHO) high-grade tumour classification and poor prognosis." (PMID 37686174, 2023). "Furthermore, they proposed circ-TXNDC11 as a potential therapeutic agent for RCC treatment, since circ-TXNDC11 silencing causes cell proliferation and invasion suppression in vitro, and reduced tumor growth in a mice model." (PMID 35813211, 2022). "Finally, in vivo, orthotopic xenotransplantation of TXNDC11-silenced GBM cells into nude rats promoted slower tumour growth and prolonged survival time." (PMID 37686174, 2023). "This indicates that TXNDC11 plays an important role in the regulation of tumour growth in vivo." (PMID 37686174, 2023).
TXNDC11 also shares sentences with these, for which no sentence is quoted: cancer (3 papers); Allergy (1); breast carcinoma (1).